SERPINB5 (serpin family B member 5)
Diseases named in the same sentence as SERPINB5 in open-access papers (continued):
Sharing a sentence is not in itself a finding about the gene and the disease.
glioma (3 papers, 2015 to 2024). A benign or malignant brain and spinal cord tumor that arises from glial cells (astrocytes, oligodendrocytes, ependymal cells). "By contrast, the mRNA and protein levels of mammary serine protease inhibitor (maspin; SERPINB5) were significantly lower in the glioma than in the normal brain tissue, and maspin expression was inversely proportional to the glioma pathological grade." (PMID 25872784, 2015).
inflammatory bowel disease (3 papers, 2017 to 2022). A spectrum of small and large bowel inflammatory diseases of unknown etiology. "On the other hand SerpinB5 is already observed in premalignant lesions—specifically serrated polyps and in inflammatory bowel disease." (PMID 29176937, 2017).
lymph node metastasis (3 papers, 2017 to 2020). "Tumor cells lacking SERPINB5 expression tend to have lymph node metastasis and invasive progression of OSCC, and patients with high levels of SERPINB5 gene expression have better survival rates than those with low expression levels of SERPINB5." (PMID 28339463, 2017).
melanoma (3 papers, 2020 to 2025). A malignant, usually aggressive tumor composed of atypical, neoplastic melanocytes. "Risk forest plot analysis revealed that SFN, PLA2G4E, SERPINB5, WWC1, PAK6, and TEAD3 were the most influential genes in promoting melanoma malignancy." (PMID 41034991, 2025).
metastatic carcinoma (2 papers, 2011 to 2024). A carcinoma which has spread from the original site of growth to another anatomic site. "Similarly, mRNAs down-regulated in the metastatic line, including mRNAs expressed by the CTGF and SERPINB5 genes, have been found to be down-regulated in various metastatic cancers, attesting to the reliability of our analyses." (PMID 21980368, 2011).
oral cancer (2 papers, 2017 to 2020). "Adjusted odds ratios (AORs) and 95% confidence intervals (CI) of clinical statuses associated with genotypic frequencies of SERPINB5 in oral cancer patients (n = 741)." (PMID 28339463, 2017). "Adjusted odds ratios (AORs) and 95% confidence intervals (CIs) of oral cancer associated with genotypic frequencies of SERPINB5." (PMID 28339463, 2017). "In the present study, TC heterozygotes of the SERPINB5 rs17071138 T/C polymorphism and CC homozygotes of the SERPINB5 rs8089104 T/C polymorphism were significantly associated with susceptibility to oral cancer." (PMID 28339463, 2017). "Adjusted odds ratios (AORs) and 95% confidence intervals (CIs) of oral cancer associated with genotypic frequencies of SERPINB5 among individuals exposed to relevant environmental risk factors." (PMID 28339463, 2017). "We identified rs17071138 T/C, rs3744941 C/T, and rs8089104 T/C gene polymorphisms of SERPINB5 (mammary serine protease inhibitor) that are specific to patients with oral cancer susceptibility and their clinicopathological status." (PMID 28339463, 2017). "In conclusion, our results suggested that heterozygotes TC of the SERPINB5 rs17071138 polymorphism may be a factor that increases susceptibility to oral cancer." (PMID 28339463, 2017). "Heterozygous TC of the SERPINB5 rs17071138 polymorphism may be a factor that increases susceptibility to oral cancer." (PMID 28339463, 2017). "The SERPINB5 gene is located on chromosome 18q21.3, and expression of the SERPINB5 gene can be modulated by regulating the initiation of transcription on the promoter region in human oral cancer cell lines." (PMID 28339463, 2017). "SERPINB5 is a potential senescence marker in oral precancerous lesions for its response to oncogene-induced senescence, and increased SERPINB5 expression plays a critical role in protecting cells against oral cancer." (PMID 28339463, 2017). "Based on genomic to phenomic investigations, we have found new genes including ADCY2, SERPINB5, and ANAPC13 linked with oral cancer that could be potential diagnostic or drug targets." (PMID 32887903, 2020). "We suggest that SERPINB5 plays an important role in modulating the progression of oral cancer." (PMID 28339463, 2017). "No studies had examined associations of SERPINB5 rs17071138 T/C, rs3744941 C/T, and rs8089104 T/C genetic polymorphisms with susceptibility to oral cancer." (PMID 28339463, 2017). "However, to the best of our knowledge, no studies have investigated the impacts of SERPINB5 rs17071138 T/C, rs3744941 C/T, and rs8089104 T/C gene polymorphisms on susceptibility to oral cancer." (PMID 28339463, 2017).
ovarian carcinoma (2 papers, 2014 to 2021). A malignant neoplasm originating from the surface ovarian epithelium. "On the contrary, over-expression of SERPINB5 was detected in two ovarian cancer cell lines including OVCAR3 and SKOV3 whereas the normal ovarian surface epithelial cells do not express SERPINB5." (PMID 25020046, 2014).
pancreatic adenocarcinoma (2 papers, 2021 to 2023). "We further reconfirmed the overexpression of genesFN1 and SERPINB5 in pancreatic adenocarcinoma patientsusing dataset PAAD deposited in The Cancer Genome Atlas." (PMID 33884102, 2021).
pancreatitis (2 papers, 2016 to 2021). Inflammation of the pancreas. "Hypomethylation of the SERPINB5 promoter distinguishes PDAC from pancreatitis." (PMID 33550277, 2021). "Importantly, expression of three of the five genes, POSTN, SERPINB5 and TMPRSS4, apparently increases gradually from healthy pancreas to pancreatitis and further rises between pancreatitis and PDAC." (PMID 26993610, 2016). "The degree of upregulation when compared to normal tissue was significantly higher in three (POSTN, SERPINB5, TMPRSS4) of five genes than compared to pancreatitis, suggesting that POSTN, SERPINB5 and TMPRSS4 expression increase gradually from healthy pancreas to pancreatitis to PDAC." (PMID 26993610, 2016).
skin cancer (2 papers, 2017 to 2024). "Reduced SERPINB5 expression has been associated with the progression of breast, thyroid, and skin cancer." (PMID 38363903, 2024).
asthma (1 paper, 2025). "Levels of SERPINB5 are increased in bronchoalveolar lavage fluid in a mouse model of asthma following a house dust mite challenge." (PMID 40131902, 2025). "The biologic importance of SERPINB5 to the pathogenesis of asthma is at present unknown, but a study has shown that mechanical compression (as might occur with bronchoconstriction) increases SERPINB5 expression in bronchial epithelial cells in vitro." (PMID 40131902, 2025). "Although the pathways that mediate PGAP3 induced ASM proliferation and contractility are not known, RNA-Sequencing of ASM expressing PGAP3 identified four genes significantly upregulated by PGAP3 that have known relevance with asthma (i.e., GATA3, ALOX5, BMP4, and SERPINB5)." (PMID 40131902, 2025).
chronic pancreatitis (1 paper, 2016). A chronic inflammatory process causing damage and fibrosis of the pancreatic parenchyma. "The detection of SERPINB5 in high-grade PanIN and PDAC and its lack of expression in normal pancreatic tissues and chronic pancreatitis suggest that SERPINB5 upregulation occurs early during the multi-step progression of PDAC." (PMID 26993610, 2016).
colorectal tumors (1 paper, 2017). "In our proteome analysis the protein with the highest level in colorectal tumors as compared to normal intestinal tissue was SerpinB5." (PMID 29176937, 2017). "While SerpinB5 was characterized as a tumor suppressor with anti-invasive and anti-angiogenic functions in several tumor types, analysis of colorectal tumors indicates increased protein levels in the tumor and an association with more aggressive disease and worse prognosis." (PMID 29176937, 2017).
COVID-19 (1 paper, 2024). A disease caused by infection with severe acute respiratory syndrome coronavirus 2. "SerpinB5, ERRa, and IGFBP-5 in COVID-19 patients were all positively correlated with PTT, and most patients had measurement levels below healthy control subjects." (PMID 38760690, 2024). "SerpinB5, ERRa, and IGFBP-5 measurements in COVID-19 patients were mainly lower than healthy controls and exhibited a positive correlation with PTT; however, similar to PCMT1, none of the correlated proteins have been linked to thrombosis previously." (PMID 38760690, 2024).
diabetic nephropathy (1 paper, 2024). "Alterations in SERPINB5 expression have been observed in UC epithelial cells, while TRIM29 has been demonstrated in promoting pyroptosis of diabetic nephropathy podiocytes through the NF-kB/NLRP3 inflammasome pathway." (PMID 38426148, 2024).
dry eye (1 paper, 2024). "A study comparing the tear fluid from pSS patients with that of non-SS dry eye subjects revealed upregulated protein metabolism involving MMP8, SERPINB5, RPLP2, CSTB, and CST3 in pSS patients compared to controls." (PMID 39408709, 2024).
esophageal squamous cell carcinoma (1 paper, 2020). Esophageal squamous cell carcinoma (ESCC) is a type of esophageal carcinoma (EC) that can affect any part of the esophagus, but is usually located in the upper or middle third. "The expression of SerpinB5 is significantly down-regulated in patients with esophageal squamous cell carcinoma." (PMID 33166290, 2020).
intraepithelial neoplasia (1 paper, 2025). A precancerous neoplastic process that affects the squamous, glandular, or transitional cell epithelium without evidence of invasion. "SERPINB5 has been confirmed as a novel serum diagnostic biomarker for high-grade intraepithelial neoplasia in GC and is involved in macrophage phenotype regulation." (PMID 40231256, 2025).
oral squamous cell carcinoma (1 paper, 2017). "A loss of SERPINB5 expression was correlated with an increased invasive potential in a human oral squamous cell carcinoma (OSCC) cell line." (PMID 28339463, 2017).
prostate adenocarcinoma (1 paper, 2021). "Further, enhanced expression of SERPINB5 and MMP9 was associated with low survival in TCGA PRAD (The Cancer Genome Atlas Prostate Adenocarcinoma) patients." (PMID 34938177, 2021).
pterygium (1 paper, 2022). A wedge-shaped fibrovascular lesion arising from the bulbar conjunctiva and extending to the cornea. "In active pterygium, genes involved with immune and inflammatory response (CXCL9 and PLA2G2D), angiogenesis (SERPINB5 and BM4), keratinization (DSG1), response to UV light (TYR) and negative regulation of apoptotic process (PIM1) are up regulated in relation to atrophic pterygium." (PMID 34997134, 2022).
rectal cancer (1 paper, 2021). A primary or metastatic malignant neoplasm that affects the rectum. "Many studies have focused on identifying genes as biomarkers associated with tumor response and survival prognosis of rectal cancer patients with pCRT, such as SERPINB5, CHD4, TCN1, VNN1, EPHA4, PCSK1, and DUOX2 genes." (PMID 33506057, 2021). "Currently, a lot of previous studies have reported that genes SERPINB5, CHD4, TCN1, VNN1, EPHA4, PCSK1, and DUOX2 as prognostic biomarkers were proven to correlate with poor tumor response and survival prognosis in patients with rectal cancer receiving pCRT." (PMID 33506057, 2021).
squamous cell carcinoma (1 paper, 2024). A carcinoma arising from squamous epithelial cells. "By validating the expression profiles of six specific genes (MIR205HG, KRT5, KRT6A, KRT6C, SERPINB5, and DSG3), selected based on a previously established 53-gene signature, we consistently observed higher expression levels in squamous cell carcinoma (SCC) compared to adenocarcinoma (ADC)." (PMID 38612418, 2024).
tumor (95 papers, 2004 to 2026). "SERPINB5, featured among the upregulated genes, is a tumor suppressor and senescence-associated marker, the expression of which is linked to genotoxic and oxidative stress." (PMID 38491064, 2024). "It has also been proposed that SERPINB5 in CRC is associated with tumor location, poor histological differentiation, microsatellite instability, and poor prognosis." (PMID 35610288, 2022). "The mammary serine protease inhibitor (MASPIN), encoded by the human serpin family B member 5 (SERPINB5) gene, was first reported in 1994 as a tumor suppressor." (PMID 32391558, 2020). "Another unresolved issue is how SerpinB5 subcellular localization is related to its tumor suppressor activity, as nuclear SerpinB5 is associated with a good prognostic in some cases, but not in others." (PMID 27447178, 2016). "The Serpinb5 RNA abundance may protect the graft against tumor risk of ASC through cellular suppression of excess of neoangiogenesis, which may reflect on the VEGF expression and ovarian morphology." (PMID 35777300, 2022). "SERPINB5 belongs to serpin encoding serine protease which plays a vital role in tumor metastasis." (PMID 32887903, 2020). "Changes in SerpinB5 nucleocytoplasmic distribution were initially reported in several different tumor specimens, raising the hypothesis of a possible association between SerpinB5 subcellular localization and tumor progression." (PMID 27447178, 2016). "m5C modification enhances SERPINB5 mRNA stability and protein expression, promoting tumor growth, metastasis, and resistance to microtubule-targeting chemotherapeutics." (PMID 41673397, 2026). "Non-inhibitory functions have also been reported, which include hormone transport (SERPINA6, SERPINA7), blood pressure regulation (SERPINA8), and tumor suppression (SERPINB5)." (PMID 40243422, 2025). "Traditionally, SERPINB5 has been recognized for its tumor-suppressing effects in tissues such as normal mammary epithelium, where it inhibits cell proliferation, invasion, and angiogenesis." (PMID 41595468, 2025). "PanIN development coincided with the staining of classic tumor marker proteins, SERPINB5/Maspin and Muc4." (PMID 38672675, 2024). "SERPINB5 inhibits tumor-induced angiogenesis, invasion, and metastasis through direct binding to extracellular matrix components." (PMID 38363903, 2024). "Specifically, MMP9, MMP13, MMP11, and CEMIP were positively associated with the tumor immune microenvironment, while SLPI, SLC2A1, SERPINB5, HK2, CEACAM6, and CEACAM5 were negatively associated with the tumor immune microenvironment." (PMID 37234801, 2023). "Previous studies have shown that SerpinB5 can inhibit the occurrence and development of tumors, including promoting tumor cell apoptosis, inhibiting tumor angiogenesis, and inhibiting tumor metastasis." (PMID 37006240, 2023). "From the results of this study, when BTG2 was low expression and SerpinB5 was high expression, the macrophage infiltration level in tumor tissue increases, and the prognosis was poor." (PMID 37006240, 2023). "All SERPINB families are associated with tumor cell invasion, with SERPINB1, SERPINB5 and SERPINB7 being more strongly associated with invasion." (PMID 37064125, 2023). "Some studies have found that SerpinB5 can inhibit tumor cell infiltration and metastasis, promote tumor cell apoptosis, and inhibit tumor vascular growth." (PMID 37006240, 2023). "PUF60 contributes to apoptosis and transcriptional regulation, SFXN3 is a mitochondrial serine transporter, SERPINB1 regulates the innate immune response, SERPINB5 is a tumor suppressor, and STXBP2 regulates exocytosis." (PMID 36400567, 2023). "SerpinB5 was first proposed as a tumor suppressor, and the mRNA expression level was downregulated in a variety of malignant tumors compared with that in normal tissue." (PMID 37006240, 2023). "Particularly, SerpinB5 (maspin) is a tumor suppressor that inhibits metastasis in human mammary epithelial cells." (PMID 35768767, 2022).
tumor (continued). "There is evidence for recurrent DNA methylation of LAMA3 and SERPINB5 genes on the remaining copy of chromosome 18, which suggests a “second hit” common to tumor suppressor genes." (PMID 34680217, 2021). "Annexin V staining followed by flow cytometry analysis revealed that ectopic expression of SERPINB5 protected the tumor cells from radiation-induced apoptosis, and vice versa." (PMID 32005234, 2020). "A recent finding suggested that SERPINB5 function is determined by its cellular localization and that SERPINB5 plays a tumor suppressor role only when localized in the nucleus." (PMID 32005234, 2020). "SERPINB5 was reported to be a tumor suppressor by inducing apoptosis and inhibiting proliferation, invasion, and migration of tumor cells." (PMID 28339463, 2017). "Immunohistochemistry of 26 tumor specimen confirmed upregulation of SerpinB5, thrombospondin B2 and secreted protein acidic-and-cysteine-rich." (PMID 29176937, 2017). "Most of the classifier genes (TMPRSS4, POSTN, SERPINB5) have been linked to migration, invasion, adhesion and metastasis of PDAC or other cancers, specifically associated with extracellular matrix and tumor microenvironment." (PMID 26993610, 2016). "The serpin peptidase inhibitor SERPINB5 is a tumour-suppressor gene that promotes the development of various cancers in humans." (PMID 27221742, 2016). "In vitro and animal studies indicated SerpinB5 has an important tumor and metastasis suppressor activity, which was mainly associated with its effects on adhesion, migration, cell death and angiogenesis inhibition." (PMID 27447178, 2016). "Attempts to correlate tumor progression/prognostic value and SerpinB5 nuclear or cytoplasmic localization resulted in great divergences and debates." (PMID 27447178, 2016). "Nuclear localization of SERPINB5 is required for its tumor metastasis suppressor function and it was enriched at the promoter of colony-stimulating factor (CSF-1) in chromatin immunoprecipitation and associated with diminished levels of CSF-1 mRNA." (PMID 23217164, 2012). "Mammary Serine Protease Inhibitor (Maspin, SERPINB5) is a multifunctional protein possessing tumor and metastasis suppressive functions." (PMID 21931769, 2011). "SERPINB5 produces a protein also known as maspin, and is thought to be a major downstream effector for the tumor suppression effect of Tamoxifen; therefore, it is possible that CCM+DHA modulates a pathway overlapping that of Tamoxifen." (PMID 21510869, 2011). "The sequences chosen were generally amplifiable by RT–PCR only from tumour tissue, although we have shown that SERPINB5 is expressed in the normal airway basal cell." (PMID 16222316, 2005). "An intriguing subset of genes in the cornea signature has been studied in tumor metastasis models because these genes encode proteins that regulate cell-cell or cell-matrix interactions (TWIST, MMP10, SERPINB5, THBS1, CEACAM1, C4.4A)." (PMID 16168081, 2005). "One possibility is that a significant fraction of tumour over-represented genes are normally inactivated as such multipotent stem cell (like) cells differentiate, perhaps (as has been implied for SERPINB5) by promoter methylation." (PMID 15467767, 2004). "Moreover, HK2, MMP11, CDH3, PDK4, SERPINB5, and SLC2A1 expression were closely associated with tumour stages." (PMID 37234801, 2023). "In addition, low expression of SERPINB5, a component of the down-regulated ‘gland morphogenesis’ network and a protein that exhibits context-dependent oncogenic and tumour suppressor roles also positively correlated with reduced disease-free survival in PC." (PMID 36169805, 2022). "Serpinb5 is a tumor suppressor that binds directly to extracellular matrix components, suggesting that the surface binding interaction is responsible for the inhibition of tumor-induced angiogenesis." (PMID 35777300, 2022). "SERPINB5 rendered the tumor cells resistant and refractory to radiotherapy." (PMID 32005234, 2020).